NOTCH1 (notch receptor 1)
Diseases named in the same sentence as NOTCH1 in open-access papers (continued):
Sharing a sentence is not in itself a finding about the gene and the disease.
tumor (continued). "Moreover, DATS can modulate a reciprocal feedback loop between Notch1 and microRNAs, in which Notch1 inhibition further enhances the expression of tumor-suppressive microRNAs, thereby amplifying its antitumor effects." (PMID 41602823, 2026). "In this work, comprehensive experiments unequivocally demonstrate that NOTCH1 is a tumor suppressor in HNSCC regardless of mutation or activation status and that it reduces CSC frequency." (PMID 41989846, 2026). "NOTCH1-ICD was also detected in tumor endothelial cells, suggesting potential vascular mimicry." (PMID 42131103, 2026). "It should also be noted that in some cellular contexts, Notch1 functions as a tumor suppressor." (PMID 40358161, 2025). "Notch1 loss in the skin sustains GLI2 and β-catenin activation, fostering BCC-like tumor formation." (PMID 40399946, 2025). "Furthermore, in vitro treatment of BC MCF7 cells with BFT prior to injection in mice significantly accelerated tumor growth and metastasis through the β-catenin and Notch1 signaling pathways." (PMID 40599853, 2025). "Practically, our data suggest that a NOTCH1-ICD IHC assay could be implemented in the clinic, as it is tumor specific, and NOTCH1-ICD is expressed in a sizable percentage (~30%) of SCLC patient tumors." (PMID 40627448, 2025). "The NOTCH1 and Wnt/β-catenin signaling pathways are essential for stem cell renewal and differentiation, and their aberrant activation is a crucial event in tumor occurrence and tumor stem cell differentiation." (PMID 40296919, 2025). "Overall, tumor infiltration by CD8+ cells was higher in the group with Notch1 mutations than in the group without." (PMID 41026775, 2025). "To explore whether Notch1 functions as a tumor suppressor or oncogene, we performed cell growth and cell invasion assays in the presence of Notch inhibition via DAPT treatment or siRNA‐mediated Notch1 knockdown in OSCC cell lines." (PMID 41026775, 2025). "Notch1 expression was detected in tumor and stromal cells of 92% of cases." (PMID 40060224, 2025). "This suggests that tumor cells with high NOTCH1 expression may have restricted B cell differentiation due to the inhibition of these ligand-receptor pathways." (PMID 41306984, 2025). "Specifically, NOTCH1 may be tumor-suppressive and inhibit the epithelial-to-mesenchymal transition (EMT), while NOTCH2 may be tumor-promoting for the EMT procedure." (PMID 40277814, 2025). "Moreover, in immunocompetent mice, KP1 TAS1440 Notch1-KO cells induced tumor growth, whereas tumors induced from Notch1 WT cells regressed." (PMID 40627448, 2025). "In addition, the expression of the NOTCH1 target gene p21 was also successfully evaluated in 155 out of 165 tumor samples." (PMID 41009728, 2025). "As a core protein of the pathway, NOTCH1 was highly expressed in tumor tissues." (PMID 41306984, 2025). "It has also been shown that this pathway is involved in the process of epithelial–mesenchymal transition, but the NOTCH1 gene itself may act both as an oncogene and as a tumor suppressor." (PMID 41300768, 2025). "Moreover, compared with the Rad group, the tumor volume and growth rate in the oe-NOTCH1+Rad group were significantly increased (all p<0.05)." (PMID 41306984, 2025). "Therefore, Notch1 functions as a tumor-suppressive regulator within the homeostatic SSC niche by preventing hyperproliferation." (PMID 40399946, 2025).
tumor (continued). "Notch1 and Notch2 were undetectable, whereas Notch4 was noted in limited number of tumor cells." (PMID 39548190, 2025). "NOTCH1 protein expression was detected in 35% of OSCC patient specimens, which was significantly associated with advanced disease stages, neck lymph node metastasis, poor tumor differentiation, and a second primary tumor." (PMID 41009728, 2025). "Emerging evidence indicates that periodontal pathogens, particularly P.g., may undermine efficacy of conventional anti-cancer therapies by promoting chemoresistance and enhancing tumor adaptability via pathways regulated by Notch1 and IL-6." (PMID 40924302, 2025). "highlighted the pivotal role of Notch1 signaling in modulating the tumor immune microenvironment." (PMID 41026775, 2025). "This study also found that NOTCH1 mRNA is significantly upregulated in AK compared to healthy skin, suggesting that NOTCH1 may have a carcinogenic role in AK, contrary to its presumed tumor-suppressive role in cSCC, where NOTCH1 is typically inactivated." (PMID 39925808, 2025). "Leveraging advanced bioinformatics techniques, the identification of 12 crucial genes (ETNK1, BICRA, IL-1R1, KDM3A, ARID2, GSK3β, EZH2, NOTCH1, SMARCA4, FOS, CREB1, CASP3) associated with the tumor-suppressing miR-101-3p network stands out as a notable achievement." (PMID 40074445, 2025). "Both Notch 1 and 2 were significantly decreased in KO, compared to Wt U251 tumours." (PMID 41226720, 2025). "For example, NOTCH1 is linked to LNM and tumor progression in LSC patients." (PMID 40231252, 2025). "NOTCH1 expression levels in blood and tumor tissues by subtype and stage." (PMID 40672020, 2025). "In addition, the forced expression of the tumor-suppressive miR-181c-5p negatively regulates the oncogenic Notch1 signaling in TNBC." (PMID 40486870, 2025). "Of those, five patients (71%) exhibited high tumor‐infiltrating CD8+ T cells and Notch1 mutation." (PMID 41026775, 2025). "High NOTCH1 mRNA expression was detected in one-third of the tumours and was associated with negative hormone receptor status and high uPA/PAI-1 status." (PMID 39153127, 2025). "In OSCC samples, we retrospectively examined IHC data with or without Notch1 mutations in cases with high CPS using clinical samples of tumor‐infiltrating CD8+ T cells." (PMID 41026775, 2025). "In addition, the EMT process of tumor cells is frequently accompanied by the activation of the NOTCH1 pathway." (PMID 40530904, 2025). "The NOTCH1 gene, a key regulator of cell differentiation and apoptosis, showed higher mutation ratesin OSCC than in LSCC, which is consistent with earlier findings that implicate its dual role as both oncogene and tumor suppressordepending on tissue context." (PMID 40978632, 2025). "Notably, co‐administration of the autophagy inhibitor Chloroquine restored the anti‐tumor efficacy of the WSGC peptide despite Notch1 overexpression." (PMID 40830080, 2025). "Additionally, Notch1 activation stimulates tumor cell growth and enhances survival by regulating the expression of cyclins (such as Cyclin D1) and anti-apoptotic proteins (such as Bcl-2)." (PMID 40621472, 2025). "Studies indicate upregulation of NOTCH1 expression in cSCC, suggesting that NOTCH1 may function as both a tumor suppressor and a facilitator, exerting both tumor-suppressive and tumorigenic effects in cSCC." (PMID 39925808, 2025). "The expression of Notch1 varied depending on the OSCC cell line phenotype, and Notch1 mutation was significantly correlated with tumor growth but not with tumor infiltration." (PMID 41026775, 2025). "Increasing evidence supports a tumour‐suppressive role for Notch‐1 signalling in NE tumours." (PMID 40847555, 2025). "Tumours with high NOTCH1 mRNA expression may be less sensitive to cytotoxic treatment and downregulation of the Notch signalling pathway (e.g. by γ-secretase inhibitors) may be valuable for eBC therapy as an individualised treatment option." (PMID 39153127, 2025).
tumor (continued). "In CRC, Notch1 and Notch2 have opposite roles in determination of the tumor biological behavior; Notch1 and Notch2 are independent adverse prognostic predictors, with a synergistic effect of positive Notch1 and negative Notch2 co-expression on predicting poor overall survival." (PMID 41294868, 2025). "Tumours with RREB1 mutations predominantly (but not exclusively) also had NOTCH1 mutations (n = 71/86)." (PMID 41419736, 2025). "We found that Notch1 protein was markedly upregulated in tumor tissue compared to normal." (PMID 41027955, 2025). "We then assessed the correlation between Notch1 mutations and CD8+ T cell tumor infiltration." (PMID 41026775, 2025). "Finally, we established a subcutaneous tumor-bearing mouse model to verify the effect of NOTCH1 on radiosensitivity in vivo." (PMID 41306984, 2025). "Strong gain-of-function mutations in NOTCH1 leading to ligand-independent accumulation of NICD in the nucleus is a common event in human cancers, and expression of a truncated NICD in many different cell types in mice can drive spontaneous tumor formation." (PMID 38043798, 2024). "Thus, ablation of the Notch1‐p15‐mediated tumor suppression by ANXA1 provided a novel mechanism of AML proliferation." (PMID 39447086, 2024). "Combination therapies that inhibit the FGFR-mitochondrial metabolism-Notch1 axis may then limit the growth of tumour stem cell subpopulations and enhance the anti-tumour effects of TORC1/2 inhibitors." (PMID 40135140, 2024). "Targeting molecules of the NOTCH1 pathway may provide insight into exploring novel drug targets for tumor angiogenesis." (PMID 38532427, 2024). "Finally, Notch1 has been shown to be required for tumor intrinsic functions such as growth and metastasis." (PMID 39491031, 2024). "Research has shown elevated levels of Notch expression in tumor cells compared to the adjacent hepatic parenchyma, with variable distribution in the nucleus and cytoplasm: Notch 1 and 4 are expressed in both the nucleus and the cytoplasm, while Notch 2 and 3 are expressed only in the cytoplasm." (PMID 38927059, 2024). "A previous study revealed that Notch1 could affect tumor metastasis by regulating CDH family members, such as E-cadherin." (PMID 39172098, 2024). "Thus, we evaluated the expression of Notch1 and Notch2 to further explore the molecular mechanism by which the 3D microenvironment in the MC-B hydrogels regulates tumor aggressiveness in PC." (PMID 39057404, 2024). "Furthermore, in vivo investigations demonstrated that rescuing the expression of Notch1 attenuated the reduction in tumour growth induced by PSMD7 knockdown." (PMID 38494478, 2024). "In HNSCC, NOTCH1 has been identified as a tumor suppressor gene." (PMID 38237211, 2024). "Evidence has revealed the core role of Notch1 signalling in tumor malignant behavior." (PMID 39172098, 2024). "We identified a prominent role of the NOTCH1 pathway in regulating tumor angiogenesis." (PMID 38532427, 2024). "Previous studies have indicated that NOTCH1 can function as a tumor suppressor in skin, where its activation may inhibit keratinocyte proliferation and promote differentiation." (PMID 39063983, 2024). "Notably, NOTCH1 is the most frequently detected member of the NOTCH receptor family in tumor tissues and is the most widely studied." (PMID 39117671, 2024). "Finally, curcumin decreased the expression of the microRNAs Notch1 miR-34a and miR-21 and upregulated the tumor suppressor miRNA let-7a." (PMID 39206407, 2024). "Moreover, the results suggest that Notch4 function and signaling differ substantially from those of Notch1, which suppresses tumor angiogenesis and activates canonical signaling." (PMID 38984877, 2024). "Additionally, knocking down Ndrg1 in BLM tumor organoids reduced secretory progenitor marker gene expression (Sox4, Atoh1, Dll1, Notch1), but increased enterocyte marker gene expression (Cdhr2, Aqp8)." (PMID 38893159, 2024).
tumor (continued). "However, more experiments should be conducted to fully understand the specific mechanisms of the Notch-1/IRE1/XBP1s signaling pathway in tumor development and immune escape." (PMID 38261741, 2024). "Gene expression analyses across these cell clusters confirmed that Ascl1/GFP, along with ASCL1 canonical NOTCH signaling target genes (Dll3, Notch1, Hes5) and the bHLH E-protein co-binding partners (Tcf4, Tcf12) were significantly elevated in Ascl1-OE tumor cells compared to control." (PMID 39609428, 2024). "One TNBC tumor had a stop-gain in NOTCH1, a dual-role gene (OG/TSG)." (PMID 39208653, 2024). "Another outstanding question relates to how Notch1 and Notch4 signaling overlaps in tumor ECs." (PMID 38984877, 2024). "Our investigations show that Notch1 expression was elevated in TSCC patient tumor tissues compared to non-tumor tissues, which may be driving carcinogenesis." (PMID 38866828, 2024). "However, in skin keratinocytes, Notch1 has been attributed a paradoxical ‘tumor suppressor’ role, although the precise mechanism underlying this unique function remains controversial." (PMID 39063983, 2024). "Based on the novel mechanism of ablation of the Notch1‐p15‐mediated tumor suppression in AML hyperproliferation, targeting ANXA1 provides an effective approach for AML treatment, in which antagonizing ANXA1 using NICD inhibitory peptides is an effective strategy for AML treatment." (PMID 39447086, 2024). "The Polycladia crinita extract mediated its promising anticancerous action by enhancing apoptosis and mitigating inflammation via VEGF, Notch 1, NF-кB, IL-6, Cyclin D1, Caspase 9 and Caspase 3 expression/level, which manifested in promoting the total survival rate and the tumor volume decrease." (PMID 38469406, 2024). "In conclusion, Notch1 expression has a tumor suppressor role in the proliferation of SCLC cells." (PMID 40034926, 2024). "This indicates that somatic SNVs in NOTCH1, JUN, and KDR genes may cause cancer cells to develop at various speeds and result in varying localized colonization of different cell types in the tumor." (PMID 38811597, 2024). "Clinical cohort studies have indicated that Notch1 expression levels in HCC tissues are closely linked to tumor differentiation grade, metastasis, venous invasion, and tumor node metastasis (TNM) stage, with expression levels decreasing as the pathological grade of HCC increases." (PMID 39537605, 2024). "Interestingly, Notch-1 can also induce Notch-3, reflecting its context-dependent role as both a tumor suppressor and tumor promoter." (PMID 39272905, 2024). "Moreover, it has been demonstrated that the migration and invasion of tumor cells are affected by the activation or inhibition of NOTCH1." (PMID 39063983, 2024). "This tumor-suppressive activity could explain the higher NOTCH1 levels observed in benign tumors, which are less aggressive and more differentiated compared to its malignant counterparts." (PMID 39063983, 2024). "Elevated expression of Notch1 and Hes1 in HCC tissues is associated with malignant characteristics of the tumor, indicating a poor prognosis for patients, whereas reduced expression of PTEN may promote the occurrence and progression of HCC." (PMID 39537605, 2024). "This has led to the identification of Notch1 as a potential tumor suppressor in epidermal biology." (PMID 39063983, 2024). "Although a large proportion of tumour cells were found along this Dlk1/Gpc3/Afphi branch, there were a small but substantial number of tumour cells along Notch1/Tgfb1hi branch 2, which was characterized by another progenitor and stem marker: Nes (which encodes nestin)." (PMID 39112713, 2024).
tumor (continued). "Fueled by signaling pathways such as Wnt/β-catenin, Notch1, and Hedgehog, BCSCs proliferate and differentiate into tumor-stimulating cells, contributing to tumor-stimulating microenvironments via the actions of angiogenesis, extracellular matrix (ECM) formation, and drug discharge pumps." (PMID 39123362, 2024). "Furthermore, endogenous ANXA1 promoted the proliferation of AML cells in vitro and in vivo through the ablation of Notch1‐p15‐mediated tumor suppression." (PMID 39447086, 2024). "Similarly, groups of SeNPs loaded with P. crinita extract (25, 50 mg/kg) showed Notch1 expression lessened (56.4% and 72.3%, %, respectively) when compared with a tumor control group." (PMID 38469406, 2024). "The repurposing effort of using these small molecules in tumors with NOTCH1 mutations other than T-ALL, suggests that targeting Notch1 trafficking could be equally effective across various tumor types." (PMID 38255842, 2024). "Moreover, we found poor tumor differentiated patients with high NOTCH1 had a low survival rate at a 10 year follow up." (PMID 37859809, 2023). "Mechanistically, activation of Notch1 signaling in tumors cells by Jagged1-expressing macrophages leads to prolonged nuclear retention of the NF-κB transcription factor p65, and subsequent increase of MenaINV expression in tumor cells." (PMID 37024946, 2023). "However, in Pten-null background, the loss of either Notch1 or Notch2 appeared to accelerate BRAFV600E-induced tumor development, suggesting a tumor suppressor role for Notch1 and Notch2 in BRAFV600E/Pten-null driven melanomagenesis." (PMID 36672468, 2023). "Different studies have suggested that NOTCH1 is a tumor suppressor or conversely may promote esophageal carcinogenesis." (PMID 36658434, 2023). "The grading and staging of tumours were compared with Notch1 expression." (PMID 37489207, 2023). "This may offer a potential targeted therapy against the Notch signalling pathway in tumours that strongly express Notch1." (PMID 37489207, 2023). "However, Notch1 and Notch2 can delay tumor development and inhibit their growth once BRAF-induced tumors are initiated in Pten-null mice." (PMID 36672468, 2023). "Deletion of Notch1 reduced tumor growth, an effect recapitulated by anti-NOTCH1 antibody treatment." (PMID 36658434, 2023). "Endothelial Notch1 activation in the primary tumor induces two essential metastatic programs." (PMID 37887354, 2023). "Additionally, a high trend towards significance was also found between DLL3 tumor expression (ρ = −0.154; p = 0.09) and NOTCH1 expression." (PMID 37893184, 2023). "The NOTCH1 alterations (12%, 5/42 cases) are noteworthy as NOTCH1 may be either tumor suppressive or oncogenic." (PMID 37095160, 2023). "Since NF-κB signaling is required but not sufficient to induce MenaINV expression to the levels achieved by the macrophage, we hypothesized that macrophages induce MenaINV expression in tumor cells through cooperation of Notch1 and NF-κB." (PMID 37024946, 2023). "On the other hand, observations on the role of NOTCH1 as an oncogene or as a tumor suppressor gene assume different functions in carcinogenesis and, therefore, that there must be other interactions within the tumor microenvironment that influence or alter the expression of this gene." (PMID 37008245, 2023). "Our study also found that NOTCH1 was activated as a tumor suppressor after treatment with CBL0137." (PMID 36691066, 2023). "Altogether, our work identifies a potent Notch1-Ripk4-Irf6-Elovl4 tumor suppressor axis." (PMID 36765696, 2023). "In a mouse model of squamous esophageal tumorigenesis, Notch1 blockade reduced premalignant tumor growth, suggesting that it might be an effective prevention strategy for the disease." (PMID 36658434, 2023). "Further experiments focused on the tumor-suppressing Notch1 pathway at the transcriptional level." (PMID 36879115, 2023).